FOXK1 (forkhead box K1)
Diseases named in the same sentence as FOXK1 in open-access papers (continued):
Sharing a sentence is not in itself a finding about the gene and the disease.
triple-negative breast carcinoma (8 papers, 2020 to 2025). An invasive breast carcinoma which is negative for expression of estrogen receptor (ER), progesterone receptor (PR), and human epidermal growth factor receptor 2 (HER2). "LncRNA HUMT recruits YBX1 to form a new transcriptional complex and activates the expression of forkhead box k1 (FOXK1) in triple-negative breast cancer, thereby promoting lymphangiogenesis and metastasis." (PMID 40799245, 2025). "Western blot showed a higher level of FOXK1 protein in triple-negative breast cancer patients with metastatic lymph nodes, further confirming a crucial role in lymph node metastasis." (PMID 32138762, 2020). "A study has identified that lncRNA is highly upregulated in metastatic triple-negative breast cancer, in which hypomethylation promotes tumor cell proliferation, LN metastasis, and lymphangiogenesis by activating forkhead box k1 (FOXK1)-mediated Akt/mTOR and VEGF-C signaling." (PMID 41511312, 2025). "These include FZD7 (Frizzled Class Receptor 7) in intrahepatic cholangiocarcinoma, Tumor-Associated Epithelial Mucin in lung adenocarcinoma, and FOXK1 (Forkhead Box K1) and CTP Synthase 1 in triple-negative breast cancer." (PMID 38255791, 2024). "LncRNA HUMT recruits Y-box binding protein 1 (YBX1) to form a new transcription complex and activates the production of forkhead box k1 (FOXK1), hence increasing VEGF expression (VEGFC) in triple-negative breast cancer (TNBC)." (PMID 36471363, 2022). "In triple-negative breast cancer, lncRNA HUMT hypomethylation activates FOXK1 transcription, promoting lymphangiogenesis and metastasis." (PMID 33381557, 2020).
lymph node metastasis (6 papers, 2016 to 2020). "Univariate Cox regression model analysis revealed that poor survival was significantly associated with differentiation, AJCC stage, lymph node metastasis, serosal invasion, FOXK1 expression and c-jun expression." (PMID 27882939, 2016). "In Cox univariate regression analysis, increased FOXK1 expression, poor histology differentiation, liver metastasis, advanced TNM stage, lymph node metastasis, and gallbladder stone were risk factors for OS." (PMID 32363163, 2020). "Further study indicated that HUMT exerted its function by recruiting YBX1 protein to the promoter region of FOXK1 and promoted its transcription, activating lymph node metastasis-related Akt/mTOR/VEGFC signaling." (PMID 32138762, 2020). "The co-expression of FOXK1 and FHL2 was significantly correlated with differentiation and lymph node metastasis." (PMID 27892920, 2016). "Moreover, when put these factors into Cox multivariate analysis, only lymph node metastasis, advanced TNM stage, gallbladder stone and increased FOXK1 expression were independent prognostic factors for OS in GBC patients." (PMID 32363163, 2020). "However, FOXK1 expression significantly correlated with TNM stage (P = 0.002), differentiation (P = 0.000), AJCC Stage I/II (P = 0.031), AJCC Stage III/IV (P = 0.04), tumor size (P = 0.019) and lymph node metastasis (P = 0.013)." (PMID 27223064, 2016). "Among these 91 patients, RUFY3 or FOXK1 expression in tumour samples was found to be significantly correlated with tumour differentiation, AJCC, lymph node metastasis, TNM stage and serosel invasion; however, it was not correlated with gender, age, location or tumor size." (PMID 28623323, 2017).
colon cancer (5 papers, 2016 to 2024). "In the same way, tRF3008A, a tRF derived from tRNAVal, induces the destabilization of the oncogenic transcript Forkhead Box K1 (FOXK1) in colon cancer cells." (PMID 39659673, 2024). "This study has also confirmed the significance of XIST/miR-497-5p/FOXK1 in the pathogenesis of colon cancer." (PMID 34179019, 2021). "We also identified for the first time the role and functional pathway of FOXK1 in promoting EMT in colon cancer." (PMID 27223064, 2016). "Another study in colon cancer cells has demonstrated over-expression of XIST and FOXK1, while down-regulation of miR-497-5p." (PMID 34179019, 2021). "However, the role of FOXK1 proteins in colon cancer development and progression remains unknown." (PMID 27223064, 2016). "Second, we found that the downregulation of FOXK1 decreased FHL2 expression, whereas downregulation of FHL2 decreased FOXK1 expression in three colon cancer cell lines." (PMID 27892920, 2016). "We then examined the expression of FOXK1 in 10 pairs of human colon cancer tissues and matched non-cancerous colonic mucosa by qRT–PCR." (PMID 27892920, 2016).
esophageal cancer (4 papers, 2019 to 2023). A primary or metastatic malignant neoplasm involving the esophagus. "It is reported that overexpression of FOXK1 inhibits apoptosis of esophageal cancer cells and promoted cell proliferation and migration." (PMID 30744670, 2019). "FOXK1 has been proved to play an oncogenic role in a variety of cancers; however, its role and molecular mechanisms in the progression and radiosensitivity of esophageal cancer are not well clarified." (PMID 37173384, 2023).
gallbladder cancer (4 papers, 2020 to 2025). "FOXK1, its paralog, has been linked to the progression of gastric, colorectal, and gallbladder cancer, and the 2 TFs share structural homology and certain functions." (PMID 35349489, 2022). "FOXK1 activates the AKT/mTOR signaling pathway and promotes hyperplasia and metastasis of gallbladder cancer." (PMID 39981141, 2025).
melanoma (3 papers, 2020 to 2021). A malignant, usually aggressive tumor composed of atypical, neoplastic melanocytes. "Nevertheless, our data demonstrate that nuclear DLC1 is clinically associated with FOXK1 to promote melanoma invasion and metastasis through cooperative activation of MMP9 expression." (PMID 32214200, 2020). "To further unravel the molecular mechanisms by which DLC1 associates with FOXK1 to regulate melanoma metastasis, we undertook RNA-seq analysis of both DLC1 KD and FOXK1 KD A375 cells to identify changes in gene expression compared with scrambled control." (PMID 32214200, 2020). "Mechanistically, mass spectrometry analysis identified a DLC1-associated protein, FOXK1 transcription factor, which mediated oncogenic events in melanoma by translocating and retaining DLC1 into the nucleus." (PMID 32214200, 2020). "Here, we demonstrate that DLC1, which is known to function as a tumor suppressor in various cancer types, plays oncogenic roles in melanoma, through the association of transcription factor FOXK1 in the nucleus for cooperative activation of MMP9 expression to promote invasion and metastasis." (PMID 32214200, 2020). "Altogether, these results suggest that FOXK1 functions as an oncogene in melanoma progression likely through partnering with DLC1 in the nucleus." (PMID 32214200, 2020). "Consistent with its expression change in RNA-seq, we confirmed the downregulation of MMP9 at the mRNA and protein levels in both DLC1 KD and FOXK1 KD melanoma cells." (PMID 32214200, 2020). "In summary, this is the first report showing nuclear-localized DLC1 to function as an oncogene through FOXK1 recruitment to cooperatively transactivate MMP9 expression for promoting melanoma invasion and metastasis." (PMID 32214200, 2020). "Conversely, OE of FOXK1 (FOXK1 OE) promoted melanoma tumorigenicity, growth, and metastasis both in vitro and in vivo." (PMID 32214200, 2020). "Our results identified MMP9 as one of the downstream targets to mediate the roles of DLC1 and FOXK1 in promoting melanoma cell invasion and metastasis." (PMID 32214200, 2020). "Mechanistically, DLC1 was essential for FOXK1 occupancy to the promoter region of MMP9, and both DLC1 and FOXK1 acted cooperatively to transactivate MMP9 expression for melanoma invasion and metastasis." (PMID 32214200, 2020). "RNA-sequencing profiling studies further revealed MMP9 as a direct target of FOXK1 through DLC1-regulated promoter occupancy for cooperative activation of MMP9 expression to promote melanoma invasion and metastasis." (PMID 32214200, 2020). "Besides, immunofluorescence staining showed predominant nuclear localization of endogenous DLC1 and FOXK1 in melanoma cells, suggesting that DLC1 is likely to associate with FOXK1 in the nucleus." (PMID 32214200, 2020). "Similarly, OE of both DLC1 and FOXK1 also further enhanced the invasiveness of DLC1 KD melanoma cells than OE of each factor in vitro." (PMID 32214200, 2020). "Taken together, the data suggest that DLC1 and FOXK1 function in a cooperative manner to transactivate MMP9 promoter activity as well as MMP9 functions downstream of DLC1 and FOXK1 to promote melanoma invasion in vitro." (PMID 32214200, 2020). "To correlate the clinical relevance of DLC1, FOXK1, and MMP9 expression, we analyzed their expression in a melanoma tissue microarray composed of 50 cores of metastatic melanomas." (PMID 32214200, 2020). "Consistently, DLC1, FOXK1, and MMP9 exhibited a high correlation of expression in melanoma patients’ samples and cell lines." (PMID 32214200, 2020). "We demonstrated that FOXK1 was crucial for DLC1 nuclear translocation and retention to orchestrate oncogenic programs in melanoma." (PMID 32214200, 2020). "To further substantiate the cooperative action of the DLC1–FOXK1 complex in regulating MMP9 expression and promoting melanoma invasiveness, we examined the ability of DLC1 OE, FOXK1 OE, and both to restore MMP9 expression and melanoma invasion in DLC1 KD cells." (PMID 32214200, 2020).
melanoma (continued). "Indeed, endogenous DLC1 was found to be localized in the cytoplasm of FOXK1 KD1 and KD2 melanoma cells compared with its nuclear localization in the scrambled control, suggesting that FOXK1 is required for retaining DLC1 in the nucleus." (PMID 32214200, 2020). "Chromatin immunoprecipitation (ChIP) assay confirmed a higher binding affinity of FOXK1 for the consensus motif within the MMP9 promoter in melanoma cells compared with IgG control, whereas it did not bind to another DNA fragment without the motif, indicating the specificity of the binding." (PMID 32214200, 2020). "Importantly, DLC1 expression levels remained unaltered in both FOXK1-depleted and FOXK1 OE melanoma cells, indicating that DLC1 expression is not regulated by FOXK1." (PMID 32214200, 2020). "Interestingly, we found that FOXK1 could also physically interact with USP7 and the PRC2 complex in A375 melanoma cells (data not shown), suggesting that USP7 and PRC2 may share similar transcription factors and thus respond to the same signal pathways." (PMID 33849069, 2021).
osteosarcoma (3 papers, 2016 to 2022). A usually aggressive malignant bone-forming mesenchymal neoplasm, predominantly affecting adolescents and young adults. "In osteosarcoma, miR-186-5p attenuates cell proliferation, invasion, and metastasis by targeting Forkhead Box K1." (PMID 35959150, 2022).
pancreatic cancer (3 papers, 2019 to 2021). "Silencing MCM3AP-AS1 expression inhibits cell proliferation and colony formation by regulating the miR-138-5p/FOXK1 axis in pancreatic cancer and plays the same role by controlling the miR-211-5p/SPARC pathway in papillary thyroid cancer." (PMID 34692706, 2021). "LncRNA MCM3AP-AS1 reduces the levels of miR-138-5p and increased the expression of FOXK1, promoting cell migration in pancreatic cancer." (PMID 34692706, 2021). "Long non-coding RNA MCM3AP-AS1 promotes growth and migration through modulating FOXK1 by sponging miR-138-5p in pancreatic cancer." (PMID 33390953, 2020).
breast tumor (2 papers, 2022 to 2023). "FOXK1 significantly increased breast tumor cell proliferation via facilitating G1/S transition." (PMID 37689738, 2023). "FOXK1 induced cell migration by EMT regulation in breast tumor cells." (PMID 37689738, 2023). "To further examine the role of ID4 in cancer stemness, we knocked down ID4 in MDA-MB-468 breast tumor cells using SMARTpool siRNAs, and tested the expression of a panel of stemness genes including Twist1, Twist2, Snail, Slug, BMP2, IRF1, SOX4, Foxk1 and Notch3." (PMID 36291790, 2022).
leukemia (2 papers, 2021). A malignant (clonal) hematologic disorder, involving hematopoietic stem cells and characterized by the presence of primitive or atypical myeloid or lymphoid cells in the bone marrow and the blood. "We show that the C-terminally truncated mutant ASXL1 proteins are expressed at much higher levels than the wild-type protein in ASXL1 heterozygous leukemia cells, and lose the ability to interact with FOXK1/K2." (PMID 32683582, 2021).
non-small cell lung carcinoma (2 papers, 2022 to 2025). A group of at least three distinct histological types of lung cancer, including non-small cell squamous cell carcinoma, adenocarcinoma, and large cell carcinoma. "Additionally, USP28-mediated FOXK1 deubiquitination activates the Hippo signaling pathway to regulate cell proliferation and radiosensitivity, while targeting USP47 enhances the efficacy of KRAS G12C inhibitors in mutant non-small cell lung cancer through regulation of c-Myc deubiquitination." (PMID 41488674, 2025).
Parkinson disease (2 papers, 2023 to 2025). A progressive degenerative disorder of the central nervous system characterized by loss of dopamine producing neurons in the substantia nigra and the presence of Lewy bodies in the substantia nigra and locus coeruleus. "In Parkinson's disease (PD) model, circSV2b overexpression can reduce oxidative stress injury, protect dopaminergic neuron loss, maintain nigrostriatal function, and improve motor defects through miR‐5107‐5p‐FOXK1 (fork‐head box protein K1)‐AKT1 (serine/threonine protein kinase) signaling pathways." (PMID 37313330, 2023).
pleural mesothelioma (2 papers, 2018 to 2021). A neoplasm that arises from the mesothelial cells of the pleura. "For example, analysis of 407 pleural mesothelioma cases and 389 controls with a comprehensive history of asbestos exposure revealed an increased risk of abnormalities in chromosomal region 7p22.2, which includes the gene encoding the Forkhead box protein K1 (FOXK1) that interacts with BAP1." (PMID 33802313, 2021). "For example, analysis of 407 pleural mesothelioma cases and 389 controls with a comprehensive history of asbestos exposure revealed an increased risk of abnormalities in chromosomal region 7p22.2, which includes the gene encoding Forkhead box protein K1 (FOXK1) that is known to interact with BAP1." (PMID 30060501, 2018).
alcoholic cirrhosis (1 paper, 2024). "Hypermethylated DMRs observed in alcoholic cirrhosis and alcoholic HCC were found in forkhead box K1 (FOXK1), zinc finger CCCH-type containing 3 (ZC3H3), nuclear factor IX (NFIX), histone deacetylase 4 (HDAC4), and tetraspanin 9 (TSPAN9) genes." (PMID 38302914, 2024).
autism (1 paper, 2023). Persistent deficits in social interaction and communication and interaction as well as a markedly restricted repertoire of activity and interest as well as repetitive patterns of behavior. "Additionally, FOXK1 has been associated with autism and delayed development in several studies." (PMID 37234859, 2023).
Cholecystitis (1 paper, 2020). The presence of inflammatory changes in the gallbladder. "we found that FOXK1 expression was significantly up-regulated in GBC tissues compared with the cholecystitis gallbladder epithelial tissues and gallbladder normal tissue adjacent tumor." (PMID 32363163, 2020). "On the contrary, only 6% (4/64) of the cholecystitis specimens showed strong staining of FOXK1 protein." (PMID 32363163, 2020).
cholelithiasis (1 paper, 2020). The presence of crystallized deposits forming in the gallbladder or biliary tree, primarily composed of cholesterol, bilirubin, and bile. "Immunohistochemistry analysis revealed that the positive staining of FOXK1 was mainly observed in the nucleus of cells and FOXK1 expression was significantly higher in tumor specimens compared with that in cholelithiasis tissues." (PMID 32363163, 2020).
Cirrhosis (1 paper, 2024). A chronic disorder of the liver in which liver tissue becomes scarred and is partially replaced by regenerative nodules and fibrotic tissue resulting in loss of liver function. "Changes in the methylation and transcriptional levels of ZBTB38, ZC3H3, FOXK1, and KAZN are important for the development of fibrosis and HCC; and are therefore potential therapeutic targets and diagnostic tools for cirrhosis and HCC." (PMID 38302914, 2024).
colorectal tumor (1 paper, 2020). "A previous study indicated that LINC01503 promoted the proliferation and metastasis of colorectal tumor cells by regulating miR-4492/FOXK1 signaling." (PMID 33149738, 2020).
Hepatic steatosis (1 paper, 2025). Steatosis is a term used to denote lipid accumulation within hepatocytes. "Mice with hepatocyte-specific deletion of Foxk1 exhibit reduced lipogenic activities and increased catabolic activities, which are associated with protection from hepatic steatosis, inflammation, and fibrosis in pre-clinical MASLD models." (PMID 40228209, 2025).
HIV-1 infection (1 paper, 2015). The type species of lentivirus and the etiologic agent of acquired immunodeficiency syndrome (AIDS). "FOXK1 inhibited interferon production in Sendai virus infection, a single-stranded RNA virus, and its downregulation in early HIV-1 infection likely contributes to triggering the immune response." (PMID 26426037, 2015).
intrauterine growth restriction (1 paper, 2020). "Hypomethylation and underexpression of FOXK1 has been recently reported to be associated with intrauterine growth restriction." (PMID 32708910, 2020).
ischemic stroke (1 paper, 2025). A stroke disorder caused by obstruction of blood flow to the brain, due to thrombotic (local blood clot formation) or embolic (due to a blood clot or other material traveling from another site) event. "Our findings suggest that core transcription factors such as SOX8, KLF13, and FOXK1 may serve as crucial therapeutic targets for electroacupuncture in ischemic stroke." (PMID 40109665, 2025). "Furthermore, core transcriptional regulatory circuitries involving SOX8, FOXK1, and KLF13 were identified, highlighting their roles in the modulation of SE-mediated gene regulation by acupuncture in the ischemic stroke context." (PMID 40109665, 2025).
mesothelioma (1 paper, 2013). A usually malignant and aggressive neoplasm of the mesothelium which is often associated with exposure to asbestos. "Interestingly, FOXK1 has been reported to interact with BAP1, which was recently found to be mutated in mesothelioma." (PMID 23626673, 2013).
metastatic cancer (1 paper, 2017). A carcinoma which has spread from the original site of growth to another anatomic site. "To validate our findings in vivo, we detected RUFY3 and FOXK1 in serial sections of lymph node metastatic cancer tissues from two patients." (PMID 28623323, 2017).
renal carcinoma (1 paper, 2024). A carcinoma arising from the epithelium of the renal parenchyma or the renal pelvis. "Evermore, we examined FOXK1 expression in kidney tissues of patients with obstructive nephropathy, or in the para‐tumor kidney tissues of renal cancer patients undergoing nephrectomy." (PMID 39083268, 2024).